RNU7-180P (RNA, U7 small nuclear 180 pseudogene)
Gene: Small nuclear RNA gene on chromosome 5 (146,245,191 to 146,245,253, reverse strand). Ensembl gene ENSG00000238374.
Homologues: Paralogues in human: RNU7-136P (75% identical), RNU7-65P (75% identical), RNU7-37P (73% identical), RNU7-62P (73% identical), RNU7-95P (73% identical), RNU7-127P (71% identical), RNU7-59P (71% identical), RNU7-9P (71% identical), U7 (71% identical), RNU7-10P (70% identical), RNU7-120P (70% identical), RNU7-123P (70% identical), and 141 more.